MTOR (mechanistic target of rapamycin kinase)
Diseases named in the same sentence as MTOR in open-access papers (continued):
Sharing a sentence is not in itself a finding about the gene and the disease.
cancer (continued). "It has been reported that mTOR pathways regulate tumor cell migration and cancer metastasis." (PMID 24605059, 2014). "This concept of a biological threshold for mTOR phosphorylation was substantiated using Panc02 cancer cells in vitro, because mTOR activation was only enhanced in response to leucine under growth factor restrictive conditions (1% FBS) and not growth factor-abundant conditions (10% FBS)." (PMID 24685128, 2014). "The mTOR pathway regulates cell growth and proliferation in response to mitogen, nutrient, and energy status within the cell and is often dysregulated in various diseases, such as cancer and diabetes." (PMID 25505994, 2014). "So why mTOR is deactivated not only in contact-inhibited but also in confluent cancer cells?" (PMID 25585637, 2014). "In several solid tumors, activation of the mTOR pathway has been found to correlate with the promotion of cell proliferation, differentiation, apoptosis evasion and resistance to cytotoxic therapy in cancer cells." (PMID 25120661, 2014). "Downregulation of RICROR, which is regulated by mTORC2-induced Akt activation, reduces phosphorylation of GSK3 and cancer cell motility, suggesting that mTORC2 inhibition may abrogate the unfavorable signaling effects of mTOR inhibitors." (PMID 25003395, 2014). "Additional studies suggest that mTOR is the upstream regulator of HIF-1α in cancer cells." (PMID 25140303, 2014). "Members of the PI3K/Akt/mTor signaling cascade are among the most frequently altered proteins in cancer, yet the therapeutic application of pharmacological inhibitors of this signaling network, either as monotherapy or in combination therapy (CT) has so far not been particularly successful." (PMID 26056598, 2014). "Moreover, it has been well documented that direct or indirect inhibition of insulin (or IGF-1)/PI3K/Akt/mTOR pathway, such as rapamycin, metformin and dietary protein restriction, have cancer- preventing or treating effects." (PMID 24970814, 2014). "The phosphatidylinositol-3-kinase (PI3K)/Akt and the mammalian target of rapamycin (mTOR) signaling pathways are two pathways crucial to many aspects of cell growth and survival, in physiological as well as in pathological conditions (e.g., cancer)." (PMID 24782981, 2014). "In conclusion,this meta-analysis showed that the mTOR polymorphisms (rs2295080 and rs11121704) were associated with cancer risk and clinical outcomes of cancer patients, respectively, and no any association was found for the rs2536 polymorphism." (PMID 24816861, 2014). "Concerning PI3K targeting, it has been generally accepted that the dual targeting of PI3K p110α and mTOR is the most potent strategy to inhibit the pathway in a variety of human cancers, including GBM, by circumventing some of the feedback loops which control tumor resistance to mTOR inhibitors." (PMID 24718026, 2014). "mTOR is an evolutionarily conserved serine-threonine kinase with a central role in cell growth, invasion, and metastasis of tumors, and is activated in many cancers." (PMID 24818169, 2014). "To test this hypothesis, we performed targeted exome sequencing cells using a 202 gene panel that includes mTOR as well as multiple other cancer-related genes." (PMID 25261369, 2014). "mTOR has also been investigated as a target for cancer therapy." (PMID 25009644, 2014). "Constitutive activation of PI3K/mTOR signaling may contribute to the survival advantage of human cancer cells, in part through the induction of antiapoptotic regulatory proteins." (PMID 24695632, 2014). "Furthermore, there has been conjecture that cancer cells rely on the activation of the PI3K/Akt/mTOR pathway for survival, because of the adverse conditions in which they grow, such as acidic or hypoxic conditions." (PMID 25334061, 2014). "These new findings suggest that targeting metabolism may be a novel strategy of mTOR inhibitor to suppress the growth of cancers." (PMID 24626155, 2014).
cancer (continued). "Similarly, a study analyzing lifespan and end-of-life pathology in hypomorphic mTOR mutant mice reported a clear reduction of malignant tumors in the mutants, while infections were more common in these animals." (PMID 25015322, 2014). "Inhibition of certain components of the PI3K/Akt/mTOR pathway may slow down or even stop cancer growth or sensitize cancer cells to chemotherapy." (PMID 25334061, 2014). "However, the use of rapamycin and the corresponding analogs in the clinic has revealed that the mTOR signaling pathway is embedded in a network of signaling cross-talk and feedback mechanisms, significantly reducing the effectiveness in cancer treatment." (PMID 25289085, 2014). "However, recent reports have demonstrated that inhibitors of mTOR are capable of increasing MEK/ERK activation and its associated proliferation and survival signaling in cancer cells." (PMID 25180793, 2014). "Preternaturally cancer-resistant naked mole-rats have naturally have low insulin and mTOR signaling that may protect them against tumorigenesis." (PMID 25553771, 2014). "Therefore, the use of mTOR as a therapeutic target is becoming increasingly significant in cancer research." (PMID 25009644, 2014). "Both mammalian target of rapamycin (mTOR) and NF-κB signaling are linked with cell growth and commonly deregulated in cancers, but no disruption in these pathways was detected following treatment." (PMID 24409098, 2014). "Given that an overactive PI3K pathway is frequently implicated in the development and progression of a variety of malignancies, therapeutic targeting of crucial mediators along the PI3K signaling axis, such as mTOR, is an attractive strategy for cancer therapy." (PMID 24916546, 2014). "In summary, OA suppresses the activation of mTOR signaling in cancer cells." (PMID 24626155, 2014). "The AMPK pathway plays an important regulatory role in the metabolism of both normal and malignant cells, and AMPK activators have been shown to suppress mTOR activity, negatively regulating malignant transformation and cell proliferation in various cancer cell types." (PMID 25137374, 2014). "The PI3K/AKT1/mTOR pathway was related to the cancer call metastasis and proliferation." (PMID 24757677, 2014). "Interestingly, statins induce autophagy activation via the adenosine monophosphate-activated protein kinase (AMPK)-mammalian target of rapamycin (mTOR) signaling pathway in cancer cells." (PMID 24815071, 2014). "Given that PI3K/Akt/mTOR pathway drugs have successfully progressed into clinical use for human cancer, similar drugs may have clinical utility in ocular neovascularization." (PMID 25144531, 2014). "Several reports showed that tumor microenvironment may influence chemoresistance of cancer cells through dis-regulation of AKT/mTOR pathway." (PMID 24327602, 2014). "Additional research is needed to ascertain the impact amino acids (BC or otherwise) have on cancer growth and muscle repair; the identification of mTOR-independent approaches to spare muscle in cachectic cancer patients; and the link between energy balance, mTOR signaling, and amino acid metabolism." (PMID 24685128, 2014). "mTOR is a serine-threonine protein kinase that plays an important role in signal transduction pathways that control cell growth and angiogenesis and has been a target to many cancer therapy approaches in-vitro and in-vivo." (PMID 24586308, 2014). "Moreover, several studies have observed a synergistic antitumor effect between PI3K or mTOR inhibitors and conventional chemotherapy agents such as cisplatin in chemo-naïve or resistant cancers like melanoma, ovarian, and nasopharyngeal cancer." (PMID 24969552, 2014). "sMEK1 co-treatment could further increase paclitaxel-induced cancer cell death by enhancing apoptosis and inhibiting the mTOR-S6K/4E-BP signaling pathways more effectively." (PMID 25153728, 2014).
cancer (continued). "It has been assumed that this may be because mTOR at the crossroad of a network of molecular pathways regulates the synthesis of proteins required for growth of cancer cells." (PMID 24818169, 2014). "Increased activation of mammalian target of rapamycin (mTOR) is observed in numerous human cancers." (PMID 25051975, 2014). "Growth-promoting pathways such as the PI-3K/mTOR pathway are involved in both cancer and aging." (PMID 25587030, 2014). "It has been observed that inhibition of mTOR results in enhanced cancer cell death." (PMID 25221930, 2014). "The PI3K/Akt/mTOR survival signaling cascade is frequently considered a promising target in modern CT, particularly as PTEN, its negative regulator, is among the most frequent mutated proteins in cancer." (PMID 26056598, 2014). "Previous studies have demonstrated that GOLPH3 could regulate tumorigenicity by enhancing activation of mTOR signaling in human cancer cells, thereby influencing cell growth, cell size and proliferation." (PMID 25104140, 2014). "About the role of these miRNA in cancer regulation, what is known is that PTEN is a tumour suppressor, mutated in sporadic and inherited tumours and involved in the inhibition of PI3K/Akt/mTOR signaling, a pathway leading to enhanced cell survival and growth in a number of human cancers." (PMID 24858274, 2014). "There is considerable interest in the potential of mTOR inhibitors for the treatment of cancer." (PMID 25201874, 2014). "Interestingly, some studies have suggested that GOLPH3 regulates cancer cells by enhancing mammalian target of rapamycin (mTOR) activity." (PMID 25286393, 2014). "In cancer cells, mTOR is inhibited due to exhaustion of the medium." (PMID 25585637, 2014). "The PI3K/AKT/mTOR signaling cascade is commonly dysregulated in human cancers." (PMID 25284964, 2013). "Furthermore, inhibition of mTOR or eukaryotic translation initiation factors (eIFs) has also been applied for cancer treatment." (PMID 23592547, 2013). "More specifically, the phosphatidylinositol-3-kinase (PI3K)/Akt/mTOR pathway plays a critical role in multiple cellular functions, including proliferation, growth, and metabolism, and this pathway is highly activated in many types of cancer." (PMID 23818925, 2013). "Results showed that simultaneous targeting of EGFR and mTOR inhibits the growth of cancer cells." (PMID 23861714, 2013). "Activation of mTOR signaling is involved in some of the cancer hallmarks and contributes to tumor growth, angiogenesis and metastasis, reinforcing the importance of considering mTOR targeting in cancer therapy." (PMID 23468988, 2013). "Evidence indicates that mTOR functions as a master switch of cellular catabolism and anabolism, thus determining whether cancer cells grow and proliferate." (PMID 24137412, 2013). "In recent years, mTOR was found to play important roles in maintaining cancer stem cells." (PMID 23667692, 2013). "Additionally, the PI3K-AKT and mTOR pathways, which are commonly activated in cancer cells, are known to enhance lipid synthesis." (PMID 23954639, 2013). "Therefore, downregulation of these miRNAs contributes to elevated activation of the mTOR pathway and malignant behaviour in cancer cells." (PMID 23434669, 2013). "Thus, it is highly important to simultaneously inhibit both mTOR and PI3K in the treatment of obesity-associated cancer." (PMID 23339750, 2013). "Although randomized data are still pending, several studies suggest an anti-cancer effect and better post-transplant survivals with the use of mammalian target of rapamycin (mTOR) inhibitors, and patients may be put on such drugs when a recurrence occurs." (PMID 22710887, 2013). "Suppression of cellular proliferation, cell cycle and cell growth by rapalogs has been investigated in many cancers, suggesting that rapalogs could serve as anticancer drugs through mTOR inhibition." (PMID 23434669, 2013).
cancer (continued). "Consequently, pathway analyses predicted that these miRNAs would regulate well-described cancer-associated signaling pathways, such as the TGF-β, Wnt, MAPK and mammalian target of rapamycin (mTOR) pathways." (PMID 24137320, 2013). "However, dual inhibition of PI3K and mTOR was effective as an antiproliferative and antitumor in some cancer cell lines and experimental tumour models." (PMID 23434669, 2013). "Reports on new cancer molecular targets indicated that some success has been achieved in the inhibition of PI3K/Akt/mTOR pathway for therapeutic purposes, but unfortunately different feedback loops were found to interrupt chemotherapeutic efficiency of the inhibitors." (PMID 24065159, 2013). "As described in other cell models, we show that PARP1 inhibition triggers AKT activation but disclose the first insight on the role of PARP1/SIRT1 balancing in the control of the AKT/mTOR axis providing a further rationale for the treatment of this aggressive cancer." (PMID 23301673, 2013). "Decreased AMPK activation has been found in some cancers and mTOR signaling is has been activated many tumors, which may become an attractive target for cancer therapy." (PMID 23300996, 2013). "The Akt-mTOR pathway, a master regulator of aerobic glycolysis and cellular biosynthesis, plays an important role in satisfying the bioenergetic and biosynthetic needs of cancer cells." (PMID 24063558, 2013). "Considering mTOR was up-regulated by radiation through miR-99b and mTOR signal pathway plays critical roles in regulating cancer cell survival, proliferation and apoptosis, we wonder whether mTOR inhibition have synergistic effects with radiotherapy." (PMID 23886294, 2013). "The multiple roles of mTORC1 and especially those correlated with mRNA translation and cell cycle has made the PI3K/Akt/mTORC1 axis an attractive target for the development of dual PI3K/mTOR inhibitors, mTOR-selective inhibitors and Akt inhibitors as anti-cancer drugs." (PMID 23459844, 2013). "We found that the protein encoding mTOR was expressed in all normal and cancer-derived samples (data not shown) whereas mTOR phosphorylation was detected at high level in 46/92 OC (50%), of which 33 were S-OC e 9 were E-OC." (PMID 23408974, 2013). "It is therefore not surprising that pivotal proto-oncogenes (for example, RAS, PI3K and Akt) and tumor-suppressor genes (for example, PTEN, NF1 and LKB1) directly regulate the activity of the mTOR pathway, and that elevated mTOR signaling has been detected in a large proportion of human cancers." (PMID 23594524, 2013). "We found mTOR complexes to be differently expressed in these cells, concluding that mTORC2 might be involved in the maintenance of the cancer stem-like phenotype, while mTORC1 might be involved in CoCSC maturation." (PMID 24185040, 2013). "We hypothesized that mTOR inhibition could potentiate the clinical activity of irinotecan by preventing the regulation of cancer cell survival." (PMID 24216984, 2013). "Consequently, inhibition of autophagy was used as a strategy to enhance the efficacy of PI3K/Akt/mTOR inhibitors in different cancers." (PMID 24244540, 2013). "The first group consists of cancer cells whose drug resistance can be overcome by exposing the cells to GCs in combination with drugs that target protein kinases such as Akt, mTOR, Src, ALK, and/or BCR, or drugs antagonizing Bcl-2, Bcl-XL, Mcl-1, c-Myc, or Notch." (PMID 23431463, 2013). "These include the mTOR/rapamycin/hypoxia pathway and cancer angiogenesis and metastasis." (PMID 23800380, 2013). "Therefore, mTOR has been considered to be a therapeutic target in cancer that can be targeted by metformin." (PMID 23667692, 2013). "Pathways upstream of mTOR and mTOR themselves are activated in cancer." (PMID 23758895, 2013). "mTOR appears to enhance cancer cell survival following DNA damage, thus the inhibition of mTOR after irinotecan could theoretically show synergistic activities in patients." (PMID 24216984, 2013).
cancer (continued). "Blockade of mTOR seems to be an effective anti-cancer strategy, even if it has been described to enhance AKT activity by feedback mechanisms involving RICTOR-mTOR activity that could induce undesirable compensatory resistance mechanisms." (PMID 23301673, 2013). "Of note, it is now apparent that the Akt/mTOR signaling network plays a key role in cancer stem cell biology and that CIC/CSCs display preferential sensitivity to the inhibition of this pathway, a feature that can be exploited in future investigations of WT CIC/CSCs." (PMID 23239665, 2013). "Both insulin and IGF-1 have been hypothesized to play a role on cancer promotion through the Akt/PI3K/mTOR cascade that promotes cell growth and proliferation." (PMID 24267900, 2013). "Thus, mTOR signaling pathway is central to translational regulation and is a novel target for cancer therapeutics." (PMID 23840271, 2013). "The PI3K/AKT/mTOR and RAF/MEK/ERK pathways are both heavily implicated in cancer progression." (PMID 23591839, 2013). "However, recent reports demonstrated that chloroquine targets the mTOR pathway in cancer cells inducing cell death." (PMID 23799062, 2013). "Besides the deregulation of the PI3K-Akt-mTOR signaling cascade, we recently showed that shikonin directly targets the mitochondria of cancer cells and thereby triggers apoptosis." (PMID 23861714, 2013). "Cancer cell survival following irinotecan-induced DNA damage is regulated by mTOR." (PMID 24216984, 2013). "HNSCC is characterized by persistent activation of the Akt/mTOR pathway that triggers a cascade of molecular events central to carcinogenesis including cancer cell survival, cell cycle progression, proliferation, transcription and translation, angiogenesis, invasion, and metastasis." (PMID 23815869, 2013). "Together with our previous observation that mTOR kinase is frequently upregulated via activation of oncogenic signaling, these findings demonstrate that upregulation of mTORC2 contributes broadly to the progression of human cancers." (PMID 24244675, 2013). "In addition, studies of several cancer cell lines have shown that mTOR catalytic inhibitors suppress protein synthesis and cell proliferation and induce G1 cell cycle arrest." (PMID 23434669, 2013). "mTOR signalling is often dysregulated during various human cancers, driving most tumorigenesis from mutations of negative mTOR regulators or by oncogenic mutations." (PMID 23434669, 2013). "It remains to be seen, whether these drugs will be useful in the treatment of cancers exhibiting enhanced mTOR activity resulting from deregulation of multiple signaling pathways that include LKB1." (PMID 23451056, 2013). "The inhibition of mTOR enhances the sensitivity of a broad range of chemocytotoxic agents, including cisplatin, carboplatin, doxorubicin, mitoxantrone and doxcetaxel in numerous types of human cancers." (PMID 24137412, 2013). "mTOR inhibitors block the growth of cancer cells by arresting the cell cycle in the G1 phase." (PMID 23291663, 2013). "Overexpression of HIF-1α has been reported in other cancers and may result from degradation-insensitive forms of this protein or increases in mTOR activity." (PMID 23460817, 2013). "We will focus on NFκB and mTOR as examples of topics for further research due to their significant degree of crosstalk during two pathophysiological conditions of both basic and pharmacological interests: inflammation and cancer." (PMID 23758895, 2013). "Besides its well-characterized role in promoting cell survival and growth, Akt/mTOR signaling can also stimulate metabolic pathways, such as aerobic glycolysis in cancer cells." (PMID 24280377, 2013). "In summary, we have shown that IIi may be a potential cancer therapeutic agent candidate with mTOR inhibitory activity." (PMID 23761818, 2013).